OVCH2 (ovochymase 2)
Description:
May be required for sperm ADAM3 processing and consequential sperm fertilizing ability (By similarity). In vitro, has an endopeptidase activity.
Synonyms: OVTN
Gene: Protein-coding gene on chromosome 11 (7,689,437 to 7,706,477, reverse strand). Ensembl gene ENSG00000183378.
Subcellular location: Secreted
Genetic constraint (gnomAD): Loss-of-function variants: 75 observed, 60.1 expected, observed/expected ratio (o/e) 1.25, 90% interval 1.03 to 1.51. The upper end of that interval is the gene's LOEUF score, 1.51, which puts it in group 6 of 6, group 1 being the genes least tolerant of losing a copy. Missense variants: 657 observed, 626.78 expected, observed/expected ratio (o/e) 1.05, 90% interval 0.98 to 1.12. Synonymous variants: 259 observed, 221.71 expected, observed/expected ratio (o/e) 1.17, 90% interval 1.05 to 1.29.
Homologues: Orthologues: chimpanzee OVCH2 (98% identical), macaque OVCH2 (95% identical), rabbit OVCH2 (80% identical), dog OVCH2 (78% identical), rat Ovch2 (78% identical), mouse Ovch2 (77% identical), pig OVCH2 (74% identical), guinea pig OVCH2 (73% identical), tropical clawed frog ovch2 (39% identical), zebrafish ovch2 (27% identical). Paralogues in human: PRRG4 (7% identical), PRRG1 (4% identical), PRRG3 (4% identical).
Diseases named in the same sentence as OVCH2 in open-access papers:
OVCH2 is named in the same sentence as 5 diseases in open-access papers, as found by Europe PMC text mining. Sharing a sentence is not in itself a finding about the gene and the disease. The quoted sentences say what the papers report.
breast carcinoma (1 paper, 2024). "In addition, a large number of additional detected genes did not fit into known breast cancer progression mechanisms (e.g. SYNDIG1, OVCH2, OR5P3, etc.)and further studies of these targets may yield new insights into additional mechanisms that support breast cancer progression." (PMID 38523186, 2024).
Infertility (1 paper, 2024). "Mice lacking Ovch2 or Adam28 possess abnormal sperm maturation and complete infertility or reduced male fertility, respectively." (PMID 38169386, 2024).
male infertility (1 paper, 2024). The inability of the male to effect fertilization of an ovum after a specified period of unprotected intercourse. "Our findings may finally lead to improvements in clinical diagnosis of male infertility and clinical management of men with mutations in OVCH2 and its interacting proteins, paving the way to novel strategies for the development of non-hormonal male contraceptives." (PMID 37551853, 2024).
prostate tumours (1 paper, 2015). "Several other genes at this locus, including CYB5R2, EIF3F, NLRP10, OLFML1 and OVCH2, were also found to be significantly expressed in prostate tumours in comparison with normal tissues." (PMID 26443449, 2015).
tumour (1 paper, 2021). "In the entire cohort of primary tumours, we disclosed three variants—deletions in BCLAF1 and OVCH2 and substitution in OR2T35—and 26 mutated genes that were mutated in >30% of all cases, being part of a global mutational signature of HPV+ TSCC/BOTSCC." (PMID 35008243, 2021). "The most common variants were deletions in BCLAF1 and OVCH2, both present in 12 samples each, followed by a substitution of OR2T35 found in 11 primary tumour samples." (PMID 35008243, 2021).